UBAP2 (ubiquitin associated protein 2)
Diseases named in the same sentence as UBAP2 in open-access papers (continued):
Sharing a sentence is not in itself a finding about the gene and the disease.
tumor (16 papers, 2016 to 2025). "In contrast, the transduction of sh‐circ‐UBAP2 or sh‐circ‐UBAP2#1 caused a remarkable repression in tumor growth." (PMID 33543830, 2021). "Additionally, the association of SFPQ, DDX39B, and UBAP2 with angiogenesis-related genes underscores their critical roles in tumor angiogenesis and progression, offering valuable insights for personalized treatment strategies and prognostic prediction in HCC and PRAD." (PMID 39133261, 2024). "PAICS enhances DNPB flux by recruiting UBAP2, boosting nucleotide synthesis and tumor proliferation." (PMID 40699765, 2025). "In vitro, circ-UBAP2 upr regulates cell proliferation, migration, and invasion while decreasing apoptosis and regulating tumor development in vivo." (PMID 35883576, 2022). "The reduced level of circ‐UBAP2 hampered cell proliferation, migration, invasion, and enhanced apoptosis in vitro and weakened tumor growth in vivo." (PMID 33543830, 2021). "Ubiquitin associated protein 2 (UBAP2) participates in the regulation of cellular process including apoptosis, metastasis, and tumor growth." (PMID 32464601, 2020). "In tumor tissues, UBAP2 expression varied and was strong in 34 (32.4%), moderate in 34 (67.7%), weak in 22 (21.0%), and negative in 15 (14.3%) case." (PMID 27121050, 2016). "Our results revealed that down-regulation of UBAP2 expression significantly promoted tumor growth in vivo." (PMID 27121050, 2016). "Here, we demonstrated that UBAP2 weakly expressed in tumor samples and its expression inversely correlated with prognosis of HCC patients." (PMID 27121050, 2016). "All these results suggested that circ‐UBAP2 silencing diminished tumor growth in vivo." (PMID 33543830, 2021). "Additionally, the restored expression of circ‐UBAP2 in the xenograft tumors significantly abrogated the impact of sh‐circ‐UBAP2 on tumor growth and miR‐1205 and miR‐382 expression." (PMID 33543830, 2021). "In addition, the expression of UBAP2 was significantly decreased, and the expression of cleaved caspase 3 was increased in tumor tissues following transfection with hsa_circ_0003141-shRNA1; however, this was reversed after transfection with miR-1827 inhibitor." (PMID 32464601, 2020). "Our results revealed that UBAP2-high subgroups had smaller tumor size." (PMID 27121050, 2016). "Then, we used a SC xenograft tumor model to assay the role of UBAP2 in tumor growth." (PMID 27121050, 2016). "Above data indicate that UBAP2 expression promote the tumor progression of HCCs." (PMID 27121050, 2016). "The positive staining for UBAP2 was localized in the cytoplasm of liver cells and tumor cells." (PMID 27121050, 2016). "An important question was whether circ‐UBAP2 could modulate tumor growth in vivo." (PMID 33543830, 2021). "Finally, we assayed the correlation between UBAP2 and Annexin A2 in tumor tissues." (PMID 27121050, 2016). "A previous study has suggested that UBAP2 acts as a tumor suppressor in HCC, since downregulation of UBAP2 promoted proliferation and invasion of HCC cells." (PMID 32464601, 2020). "Knockdown of UBAP2 significantly enhanced the invasion and proliferation of HCC cells in vitro and promoted tumor growth in vivo, while enforced expression of UBAP2 impaired the aggressive ability and tumor growth of HCC cells." (PMID 27121050, 2016). "However, we did not observe significantly different level of UBAP2 mRNA expression level between NSCLC tumor samples and matched normal tissues." (PMID 33882454, 2021). "Moreover, enforced UBAP2 expression in HCC cells could impair the invasive ability in vitro and inhibited tumor growth in vivo." (PMID 27121050, 2016).
cancer (14 papers, 2016 to 2025). A tumor composed of atypical neoplastic, often pleomorphic cells that invade other tissues. "UBAP2, which encodes a protein containing a ubiquitin-associated domain, serves as a critical regulator in the ubiquitination pathway and has been implicated in the progression of various malignant tumors." (PMID 41194937, 2025). "Exploring the potential roles of SFPQ, DDX39B, and UBAP2 in other cancer types will also provide more information for developing precise treatment strategies." (PMID 39133261, 2024). "As shown in previous studies, circ_UBAP2 upregulation enhances cancer cell growth, invasion, and migration, but suppresses apoptosis, thereby exerting a carcinogenic role during cancer occurrence." (PMID 35114890, 2022). "Previous studies have shown that circ-UBAP2 plays an important role in many cancers by acting as a sponge for miRNAs." (PMID 31584877, 2019). "Multivariate analysis showed that UBAP2 intensity in cancer tissues was an independent prognosticator for OS." (PMID 27121050, 2016). "Given the role of Annexin A2 in regulation of cancer development, we here focus on the relationship between Annexin A2 and UBAP2." (PMID 27121050, 2016). "UBAP2 was highly expressed in PC and involved in regulating the cancer progression." (PMID 38081815, 2023). "Furthermore, higher expression of UBAP2 in cancer tissues was correlated with good prognosis in HCC patients." (PMID 27121050, 2016). "Abnormal expression of circUBAP2 has been found in several cancer types, and a total of 90 circRNAs originating from UBAP2 have been identified, whereas specific back‐splicing sites of these circRNAs still need to be further elucidated, and they might be derived from different exons." (PMID 35170199, 2022). "This might be due to the dysregulation of circ‐UBAP2 on cancer cells." (PMID 33543830, 2021).
UBAP2 also shares sentences with these, for which no sentence is quoted: lung carcinoma (2 papers); Type 2 Diabetes (2); anemia (1); breast carcinoma (1); glaucoma (1); melanoma (1); neurodegenerative disease (1); neutropenia (1); Obesity (1); ocular hypertension (1); osteoarthritis (1); Parkinson disease (1); postmenopausal osteoporosis (1); preeclampsia (1); prostate tumor (1).